SPHK1 (sphingosine kinase 1)
Diseases named in the same sentence as SPHK1 in open-access papers (continued):
Sharing a sentence is not in itself a finding about the gene and the disease.
glioma (29 papers, 2011 to 2026). A benign or malignant brain and spinal cord tumor that arises from glial cells (astrocytes, oligodendrocytes, ependymal cells). "Firstly, SPHK1 overexpression caused FOXO3a phosphorylation, and SPHK1 knockdown caused FOXO3a dephosphorylation in glioma cells." (PMID 21625639, 2011). "Likewise overexpression of SphK1 is found in aggressive gliomas and is associated with poor survival." (PMID 28415564, 2017). "Thus, our finding provides a new insight into a possible mechanism that underlies SPHK1 induced resistance of glioma cells to apoptosis." (PMID 21625639, 2011). "The converging axis involving sphingomyelinase and sphingosine-1-phosphate, mediated by the actions of sphingomyelinase SMPD1 and sphingosine-kinase SPHK1, emerged as a pivotal factor in glioma." (PMID 42144879, 2026). "In identifying SphK inhibitors with clinical benefit, the dual SphK1/2 inhibitor safingol has been effective in combination with cisplatin in Phase 1 clinical trials against glioma." (PMID 40006080, 2025). "SPHK1 overexpression resulted in increased proliferation, invasion, and metastasis, whereas its inhibition decreased tumorigenesis in an orthotopic glioma mouse model." (PMID 40507361, 2025). "For instance, gliomas with isocitrate dehydrogenase (IDH) mutations, which are associated with lower malignancy, exhibit reduced sphingosine kinase 1 activity." (PMID 40429618, 2025). "Overexpression of SPHK1 and the resulting production of S1P correlated with malignancy, poor prognosis, and shorter survival time in different types of gliomas, especially GBMs." (PMID 39723240, 2024). "Preclinical studies have shown that SPHK1 inhibitors can suppress glioma growth by reducing S1P levels." (PMID 39723240, 2024). "For example, in gliomas with a mutation in the isocitrate dehydrogenase (IDH) gene, that are characterized by lower malignancy, reduced activity of sphingosine kinase 1 has been demonstrated, resulting in decreased S1P levels." (PMID 39408574, 2024). "Altogether, these results suggest that SPHK1 is strongly interconnected with the microglia compartment in GB, and that its enzymatic product S1P could therefore play an important role in the crosstalk between the tumor-associated macrophages/microglia (TAMs) and glioma cells." (PMID 36672428, 2023). "The exploration of TCGA datasets allowed us to link high SPHK1 levels with a pro-tumorigenic phenotype in glioma patients, which ultimately resulted in a worse survival outcome." (PMID 36672428, 2023). "While both SPHK1 and SPHK2 participate in the phosphorylation of sphingosine, the expression of SPHK1 is elevated in IDHwt glioma patients and is highly correlated with a worse prognosis compared to SPHK2." (PMID 36012521, 2022). "In gliomas, SphK1 was reported to be significantly correlated with the histologic grade of tumor, and patients with high SphK1 levels generally exhibited a poor survival time." (PMID 34305532, 2021). "In gliomas, both SphK1 and SphK2 were abnormally upregulated in tumor tissues and cell lines, and a higher expression of SphKs means lower survival times of glioma patients." (PMID 34305532, 2021). "The sphingolipid signaling pathway is also frequently activated in IDH-mutant gliomas, and inhibition of sphingosine kinase I (SphK1) with N,N-dimethylsphingosine (DNMS) specifically leads to cell death in IDH1-mutant gliomas." (PMID 34067729, 2021). "Ultimately, the response of IDH1mut gliomas to the targeting of SphK1 in order to obstruct S1P production and subsequent S1P signaling suggests that the sphingolipid metabolism plays a vital role in glioma’s growth and survival." (PMID 33050528, 2020). "Pharmacological blockade of the EGFR by gefetinib had a rather modest inhibitory effect on glioma cell proliferation whereas pharmacological inhibition of SphK1 strongly blocked proliferation and induced apoptosis of a GBM-derived neurosphere cell line." (PMID 25309325, 2014).
glioma (continued). "Taken together, these data suggest that SPHK1 acts to stimulate survival and anti-apoptotic signaling in glioma cells." (PMID 21625639, 2011). "To further delineate the correlation between SPHK1 and Bim expression in glioma, we next examined clinical primary glioma specimens for the expression of SPHK1 and Bim." (PMID 21625639, 2011). "Thirdly, the transcriptional activity of FOXO3a was regulated by the level of SPHK1 protein in glioma cells." (PMID 21625639, 2011). "We here report that dysregulation of SPHK1 alters the sensitivity of glioma to apoptosis both in vitro and in vivo." (PMID 21625639, 2011). "Nevertheless, mechanism by which SPHK1 activates PI3K in glioma cells, i.e., via a direct versus indirect interaction between two molecules, remains to be determined." (PMID 21625639, 2011). "TUNEL assay revealed that inhibition of SPHK1 activity enhanced epirubicin-induced apoptosis of glioma cells." (PMID 21625639, 2011). "In contrast, silencing SPHK1 by RNAi#2, which showed markedly decreased expression of SPHK1, dramatically enhanced UV- or adriamycin-induced cell death in glioma cells." (PMID 21625639, 2011). "The SPHK1 enzymatic activities in SPHK1 overexpressed glioma cells were markedly increased in comparison to that in vector-control cells, whereas silencing of SPHK1 led to significant decrease of SPHK1 activity." (PMID 21625639, 2011). "The SPHK1-overexpressed U87MG and LN-382 cells exhibited increased FOXO3a (Ser253) phosphorylation, in contrast, FOXO3a (Ser253) phosphorylation decreased dramatically in SPHK1-downregulated glioma cells." (PMID 21625639, 2011). "To further confirm the role of FOXO3a in regulating the expression of Bim in response to alterations of SPHK1 expression, we knocked down the expression of FOXO3a with specific siRNA in SPHK1 downregulated glioma cells." (PMID 21625639, 2011). "The number of apoptotic cells in vector-infected cells was significantly higher than that in SPHK1-overexpressing cells upon 1.0 μM adriamycin treatment, suggesting that ectopic expression of SPHK1 protected glioma cells from pro-apoptotic induction." (PMID 21625639, 2011). "It is particularly noteworthy that 24 out of 33 (72.7%) glioma samples that exhibited high SPHK1 expression displayed low expression of Bim, in contrast to the high level Bim expression in 34 out of the 49 (69.4%) glioma samples with low SPHK1 expression." (PMID 21625639, 2011). "It was also found that in a variety of tumor types, including glioma, SPHK1 mRNA and protein were significantly elevated." (PMID 21625639, 2011). "Further mechanistic study examined the expression of Bcl-2 family members, including Bcl-2, Mcl-1, Bax and Bim, in SPHK1-overexpressing glioma cells and revealed that only pro-apoptotic Bim was downregulated by SPHK1." (PMID 21625639, 2011). "Hypoxia increases the production and release of S1P in glioma cells, upregulates SphK1 that promotes the migration of endothelial cells, stimulates SphK2 expression and S1P release in adenocarcinoma cells, and stimulates SphK1 and SphK2 expression in pulmonary smooth muscle cells." (PMID 39660488, 2024). "In glioma cells, SphK1 could promote tumor cell proliferation and invasion, but inhibit cell apoptosis through the AKT pathway activation." (PMID 34305532, 2021). "In addition, siRNA to SphK1 partially inhibited EGFRvIII-induced growth and survival of glioma cells as well as ERK1/2 activation." (PMID 25309325, 2014). "Expression of EGFRvIII in glioma cells also activated and induced SphK1." (PMID 21936950, 2011). "In this context, targeting SPHK1 or its downstream signaling molecules as identified by our present study might represent new and potential strategies against human glioma." (PMID 21625639, 2011).
glioma (continued). "The phosphoryaltion level of Akt was upregulated by overexpression of SPHK1 and downregulated when SPHK1 was knocked down in U87MG and LN-382 glioma cells, suggesting a potential role of Akt in the signaling cascade that mediates FOXO3a phosphorylation/inactivation in response to SPHK1 upregulation." (PMID 21625639, 2011). "Additionally, SphK1 is upregulated by excitotoxicity and hypoxia in astrocytes and glioma cells, respectively." (PMID 21887342, 2011). "Akt seems to be essential in phosphorylating FOXO3a in current study because our results showed activation of Akt and Ser253 phosphorylation of FOXO3a in SPHK1-overexpressing glioma cells, as well as Akt inactivation and Ser253 dephosphorylation of FOXO3a in SPHK1-downregulated glioma cells." (PMID 21625639, 2011). "Collectively, our results indicate that regulation of the Akt/FOXO3a/Bim pathway may be a novel mechanism by which SPHK1 protects glioma cells from apoptosis, thereby involved in glioma tumorigenesis." (PMID 21625639, 2011). "In addition, siRNA to SphK1 partially inhibited EGFRvIII-induced growth and survival of glioma cells as well as ERK MAP kinase activation." (PMID 21936950, 2011). "Importantly, increasing SPHK1 expression in glioma cells markedly elevated Akt activity and phosphorylated inactivation of FOXO3a, which led to downregulation of Bim." (PMID 21625639, 2011). "We next confirmed the correlation between SPHK1 and Bim expression in primary glioma specimens." (PMID 21625639, 2011). "Moreover, we characterized the effect of SPHK1 on apoptotic protection by examining the cleavages of pro-caspase 3 and PARP in glioma cells expressing SPHK1." (PMID 21625639, 2011). "To further confirm the anti-apoptotic potential of SPHK1 in vivo, we decided to examine whether dysregulation of SPHK1 could alter the sensitivity of glioma cells to apoptosis in nude mice." (PMID 21625639, 2011). "Furthermore, Spearman correlation analysis showed that the correlation between SPHK1 and Bim expression was statistically significant (p = 0.021), suggesting a potential involvement of Bim downregulation in SPHK1-induced anti-apoptotic state in glioma." (PMID 21625639, 2011). "Furthermore, overexpression of SPHK1 correlated with downregulation of Bim in clinical glioma samples." (PMID 21625639, 2011). "Our observation that higher SPHK1 expression results in worse prognosis is in accordance with previous findings showing that increased SPHK1, but not SPHK2, correlates with lower progression-free survival in GB and has been associated with increased glioma grade." (PMID 36672428, 2023). "Therefore, we further investigated whether upregulation of SPHK1 could affect the expression of Bcl-2 family proteins in glioma cells." (PMID 21625639, 2011). "In glioma cells, as shown by our study, upregulated SPHK1 activates PI3K/Akt signaling and supports cell survival through modulation of FOXO3a and Bim, representing a new mechanism possibly underlying the development of glioma and probably, its resistance to pro-apoptotic therapeutics." (PMID 21625639, 2011). "Moreover, the transcriptional level of Bim was also altered by SPHK1 in glioma cells." (PMID 21625639, 2011). "Taken together, our results indicate that up-regulation of SPHK1 enhanced the resistance of glioma cells to cytotoxic reagent-induced cell apoptosis, and targeting SPHK1 through inhibition of SPHK1 activity might represent a potential therapeutical strategy for glioma treatment." (PMID 21625639, 2011). "Immunohistochemical staining also demonstrated that MMP9 and SPHK1 levels were apparently reduced, but LASS2 and TIMP2 levels were increased in glioma xenografts derived from U-87 MG-pLV-LASS2 cells compared with those derived from U-87 MG-pLV cells." (PMID 35517425, 2022). "Similar to SphK1, SphK2 also targeted the AKT pathway to regulate glioma cell proliferation and EMT." (PMID 34305532, 2021).
glioma (continued). "Further studies that aim at completely delineating the interaction between SPHK1 and PI3K/Akt will help develop new molecular targets for glioma therapy." (PMID 21625639, 2011). "Western blot analysis demonstrated that the protein levels of LASS2 and TIMP2 were apparently elevated, accompanied by reductions in SPHK1, MMP2, and MMP9 protein levels, in glioma xenografts derived from U-87 MG-pLV-LASS2 cells compared with those derived from U-87 MG-pLV cells." (PMID 35517425, 2022). "However, the predominance of SPHK1 in the context of cancer is supported by the observation that SPHK1 is up-regulated, whilst SPHK2 is downregulated, as a function of glioma malignancy." (PMID 24970218, 2014). "Moreover, the impact of SPHK1 inhibition was examined, using a specific SPHK1 inhibitor (SK1-I), on the resistance of gliomas to epirubicin treatment." (PMID 21625639, 2011). "Here, we report that the SphK1/S1P signaling pathway may act as a canonical regulator of HIF-2α expression in multiple cancer cell lineages (lung, prostate and glioma) as well as in ccRCC cell lines (CAKI-1, A498 and 786-O) representing the sub-groups found in human clinic." (PMID 26974204, 2016). "In contrast, we show here for the first time that the SphK1/S1P signaling regulates HIF-2α content and activity not only in ccRCC but also in other tumor types (lung, prostate, glioma), suggesting a possible universal regulatory role in cancer cells." (PMID 26974204, 2016).
Sepsis (28 papers, 2011 to 2026). Sepsis is defined as life-threatening organ dysfunction caused by a dysregulated host response to infection. "A study demonstrated that PF-543 alleviated lung injury caused by sepsis in acute ethanol intoxication rats by suppressing the SPHK1/S1P/S1PR1 signaling pathway." (PMID 36361531, 2022). "The increased survival rate of SphK1/2 deficient mice was accompanied by earlier recovery from sepsis-induced weight loss." (PMID 36361636, 2022). "In sepsis-associated liver injury models, co-localization of SphK1 and CaMKII-δ in Kupffer cells provide signals for CaMKII-δ autophosphorylation." (PMID 34824200, 2021). "In conclusion, SphK1 inhibition diminishes HMGB1 intracellular translocation in sepsis-associated liver injury." (PMID 33281190, 2020). "In conclusion, this study shows that SphK1 inhibition suppresses HMGB1 intracellular translocation in sepsis-associated liver injury." (PMID 33281190, 2020). "Then we confirmed the colocalization of SphK1 and CaMKII-δ in the livers of patients with sepsis-associated liver injury by immunofluorescence assay." (PMID 33281190, 2020). "We demonstrated that LPS-mediated subcellular localization of HMGB1 was blocked by SphK1 inhibition during sepsis-associated liver injury." (PMID 33281190, 2020). "Previously, we confirmed that sphingosine kinase 1 (SphK1) inhibition improves sepsis-associated liver injury." (PMID 33281190, 2020). "HMGB1 expression, intracellular translocation, and acetylation were suppressed by SphK1 inhibition in sepsis-associated liver injury." (PMID 33281190, 2020). "The colocalization of SphK1 and CaMKII-δ was verified in human liver tissues with sepsis-associated liver injury." (PMID 33281190, 2020). "Then, we confirmed the colocalization of SphK1 and CaMKII-δ in liver tissues of sepsis-associated liver injury patients." (PMID 33281190, 2020). "Sphingosine kinase-1 (Sphk-1), an enzyme present in neutrophils and macrophages, regulates proinflammatory responses associated with endotoxemia and sepsis." (PMID 23817990, 2013). "A previous study demonstrated that Sphk-1 regulates proinflammatory responses associated with endotoxin and polymicrobial sepsis." (PMID 23817990, 2013). "Activation of Sphk1 leads to subsequent production of S1P, which has been implicated in transcription factor activation and inflammatory response in diseases such as asthma, inflammatory bowel disease, and sepsis." (PMID 33602274, 2021). "Since previous studies showed that the expression of HMGB1 and SphK1 is elevated in sepsis-associated liver damage, whether HMGB1 and SphK1 are related remains unknown." (PMID 33281190, 2020). "Thus, platelets provide S1P for a short time during sepsis, which may be associated with the activation of SphK1." (PMID 37746079, 2023). "However, whether SphK1 may regulate HMGB1 translocation to mediate the development of sepsis-associated liver injury remains unknown." (PMID 33281190, 2020). "Sepsis-induced lactate accumulation promoted P300-mediated histone H3 lysine 18 lactylation (H3K18la) at the SPHK1 promoter, epigenetically enhancing its transcription." (PMID 41799201, 2026). "Pharmacological inhibition of SphK1 with PF‐543, a highly specific small‐molecule antagonist, effectively suppressed this axis both in vitro and in vivo and, importantly, alleviated sepsis‐related inflammation and multiorgan damage in animal models." (PMID 41427031, 2025). "Another study noted increased SPHK1 expression in PBMCs from patients with sepsis, and found that inhibition of Sphk1 with PF543 improved survival in a mouse model of polymicrobial sepsis." (PMID 38385743, 2024). "If systemic S1P levels were relevant for sepsis severity, SphK1−/− mice and SphK2−/− mice should demonstrate opposite outcomes post infection." (PMID 36361636, 2022).